LMNB1 (lamin B1)
Diseases named in the same sentence as LMNB1 in open-access papers (continued):
Sharing a sentence is not in itself a finding about the gene and the disease.
breast tumor (4 papers, 2016 to 2023). "Here, we provide evidence on the expression of the three TIS-associated markers, namely p21CIP1, H3K9Me3 and Lamin B1, in breast tumor samples following NAC and developed partial or incomplete response to therapy." (PMID 33948615, 2021). "There was a slight downregulation of LMNA in breast tumor tissues while LMNB1 and LMNB2 were significantly upregulated." (PMID 37218524, 2023). "In vitro experiments confirmed that lamin B1 protein expression is downregulated in breast tumor cells upon exposure to NAC and senescence induction." (PMID 35328162, 2022). "As patient samples from triple negative and HER2+ breast tumors displayed the largest differences between high SAβ-gal positive tumor cells, these samples were chosen to investigate potential differences in Lamin B1 expression." (PMID 27713152, 2016). "We investigated the correlation between lamin B1 protein expression and the overall survival of breast tumor samples that were not exposed to NAC and ones that were post-NAC." (PMID 35328162, 2022). "Furthermore, breast tumor samples that were identified as luminal A were examined and found to have a notable decrease of lamin B1 protein expression between not exposed to NAC (mean 86%, range: 50–95%) and post-NAC (mean 60%, range: 10–95%) (p value < 0.001: ***)." (PMID 35328162, 2022).
cervical cancer (4 papers, 2019 to 2025). A primary or metastatic malignant neoplasm involving the cervix. "Lamin B1 (LMNB1) limits early HPV infection in cervical cancer cells by maintaining nuclear integrity and supporting autophagy." (PMID 39949780, 2025). "Yang Z et.al GRSF1-mediated MIR-G-1 promotes EMT by directly increasing TMED5 and LMNB1 in cervical cancer cells." (PMID 33109773, 2020). "MIR‐G‐1 upregulates TMED5 and lamin B1 (LMNB1) in a GRSF1‐dependent manner and promotes malignant behavior and nuclear autophagy in the cervical cancer cells." (PMID 31418958, 2019).
Parkinson disease (4 papers, 2019 to 2023). A progressive degenerative disorder of the central nervous system characterized by loss of dopamine producing neurons in the substantia nigra and the presence of Lewy bodies in the substantia nigra and locus coeruleus. "Although lamin B1 has increased levels during the differentiation of the brain cells, during aging these levels drop leading to senescent phenotypes and inciting neurodegenerative disorders such as Alzheimer’s and Parkinson’s disease." (PMID 37720548, 2023). "For example, AD-related pathology is associated with a loss of LMNB, while knockdown of LMNB1, as well as the pore membrane protein of 121 kDa (POM121), increases α-synuclein aggregation in the nuclear envelope in early stages of apoptosis, with potential implications for Parkinson’s disease." (PMID 32630170, 2020).
spina bifida (4 papers, 2012 to 2022). A congenital neural tube defect in which vertebrae are not fully formed. "Genetic analysis demonstrated that the variant also affects neural tube closure: the frequency of spina bifida and anencephaly was reduced three-fold when wild-type lamin B1 was bred into the curly tail strain background." (PMID 23166514, 2012). "Nevertheless we cannot rule out a potential contribution of reduced Mthfd1L expression to spina bifida in the ct strain, acting to modify the Grhl3 effect, as we previously observed for a Lmnb1 variant (Deletion 18: 56909394) present in the ct genetic background." (PMID 26924399, 2016). "Although the majority of cases analyzed in the current study were spina bifida, we note that one of the mutations was present in a patient with anencephaly (cranial NTDs), suggesting that further analysis of LMNB1 may be particularly worthwhile in this group of NTDs." (PMID 23733478, 2013). "Strikingly, although exencephaly occurs at much lower frequency than spina bifida, Lmnb1 also affected the penetrance of these defects to a similar extent as spinal NTDs, with approximately 65% reduction in frequency among ct9E compared with ct8E embryos." (PMID 23166514, 2012). "However, breeding the wild-type Lmnb1 onto the curly tail strain background resulted in a threefold reduction in the frequency of spina bifida and exencephaly." (PMID 23733478, 2013).
Adult onset (3 papers, 2021 to 2022). Onset of disease manifestations in adulthood, defined here as at the age of 16 years or later. "ADLD is a rare adult-onset neurodegenerative disorder characterized by LMNB1 alterations and with no effective therapies." (PMID 34685544, 2021). "ADLD is a rare adult-onset demyelinating neurological disease characterized by LMNB1 alterations and with no effective therapies." (PMID 33034697, 2021).
atherosclerosis (3 papers, 2020 to 2024). A disease characterized by the build-up of fatty material and calcium deposition in the arterial wall resulting in partial or complete occlusion of the arterial lumen. "Traditional markers of cell senescence including p16, Lamin B1, and senescence-associated beta galactosidase (SAβG) suggest very high frequencies of senescent cells in atherosclerosis, while their removal via ‘senolysis’ has been reported to reduce atherogenesis." (PMID 34142149, 2022). "Lamin B1 downregulation was reported as a marker of VSMC senescence, and Lamin B1 was elevated in atherosclerosis." (PMID 39075604, 2024).
colonic adenocarcinoma (3 papers, 2021 to 2025). "LEF1 maintains the viability and growth of colonic adenocarcinoma cells through improving proliferation and Lamin B1 expression, and reducing apoptosis." (PMID 39200196, 2024). "LEF1 maintains the viability and growth of colonic adenocarcinoma cells through increasing proliferation, Lamin B1 expression, and decreasing apoptosis." (PMID 34639214, 2021). "Our results indicate that downregulated LEF1 impairs Lamin B1 expression and Lamin B1 plays a role in the oncogenesis and development of colonic adenocarcinoma." (PMID 34639214, 2021).
dentatorubral-pallidoluysian atrophy (3 papers, 2021 to 2024). Dentatorubral pallidoluysian atrophy (DRPLA) is a rare subtype of type I autosomal dominant cerebellar ataxia (ADCA type I). "In a mouse model of dentatorubral-pallidoluysian atrophy (DRPLA), a polyglutamine repeat-associated ataxia, canonical autophagy is inhibited, while nucleophagy-based Lamin B1 degradation and Golgi membrane-associated excretion is activated." (PMID 34564405, 2021).
HCMV infection (3 papers, 2018 to 2024). "In addition to the effect on capsid nuclear egress, the fact that LMNB1 acetylation inhibits nuclear periphery disruption may impact multiple aspects of the late stages of HCMV infection." (PMID 30470744, 2018). "Although its regulation is not yet understood during HCMV infection, LMNB1 was previously observed at nuclear membrane infoldings." (PMID 30470744, 2018). "Similar to our prior finding that lamin B1 acetylation inhibits HCMV production by obstructing virus capsid nuclear egress, the pro-viral function of SIRT2 deacetylase activity provides another instance of protein acetylation functioning in host defense during HCMV infection." (PMID 37916830, 2023).
leukemia (3 papers, 2018 to 2023). A malignant (clonal) hematologic disorder, involving hematopoietic stem cells and characterized by the presence of primitive or atypical myeloid or lymphoid cells in the bone marrow and the blood. "Within this context, we believe that Lamin B1 phosphorylation and farnesylation would be the primary therapeutic targets to control the dynamics of nuclear lamina in leukaemia and lymphoma." (PMID 28804121, 2018). "It is interesting that both the patients with LMNB1::PPP2R2B fusion carried ETV6::RUNX1 fusion, implying that LMNB1::PPP2R2B fusion played a role in the pathogenesis of ETV6::RUNX1-positive leukemia." (PMID 36612032, 2022).
lymphoma (3 papers, 2018 to 2026). A malignant (clonal) proliferation of B- lymphocytes or T- lymphocytes which involves the lymph nodes, bone marrow and/or extranodal sites. "LMNB1 encodes for a component of nuclear envelope involved in epigenetic chromatin regulation and it’s down-expressed in the majority of human germinal centre-derived lymphomas." (PMID 31017932, 2019). "Likewise, Lamin B1 downregulation has been observed in GC-derived lymphomas and myeloid malignancies, yet the functional consequences of Lamin B1 loss during B cell development remain poorly understood." (PMID 42261377, 2026). "From a translational perspective, reduced levels of Lamin B1 in FL could be developed into a robust molecular biomarker predicting transformation of indolent lymphoma." (PMID 28804121, 2018). "Here, we also show that nuclear Lamin B1 is decreased in the majority of GC-derived lymphomas." (PMID 28804121, 2018).
neural tube defect (3 papers, 2012 to 2022). A congenital defect characterized by failure of the neural tube to close completely; this results in the presence of openings in the brain or spinal cord. "In mice, polymorphism in Lmnb1 has been shown to modify risk of neural tube defects (NTDs), malformations of the central nervous system that result from incomplete closure of the neural folds." (PMID 23733478, 2013).
osteoporosis (3 papers, 2022 to 2026). A condition of reduced bone mass, with decreased cortical thickness and a decrease in the number and size of the trabeculae of cancellous bone (but normal chemical composition), resulting in increased fracture incidence. "Lamin B1-deficient BMSCs provide a promising gene-enhanced cell therapy strategy for osteoporosis." (PMID 41993718, 2026).
retinoblastoma (3 papers, 2016 to 2023). A malignant tumor that originates in the nuclear layer of the retina. "Likewise, in another retinoblastoma line, Weri-Rb 27 cells, retinal-loukoumasomes were also intimately associated with lamin B1." (PMID 27798680, 2016). "Particularly, TPX2, KIF20A, CENPA, DLGAP5, and LMNB1 of HHOs were significantly enriched by the retinoblastoma (RB) immunity downregulating PD-L1 expression pathway." (PMID 37240068, 2023).
acute lymphoblastic leukemia (2 papers, 2022 to 2025). Leukemia with an acute onset, characterized by the presence of lymphoblasts in the bone marrow and the peripheral blood. "Genotyping of potentially clinically relevant single-nucleotide polymorphisms (SNPs) in childhood acute lymphoblastic leukemia patients identified variants in the LMNB1 gene as related to the risk of relapse." (PMID 36005596, 2022).
Autoimmunity (2 papers, 2021 to 2025). The occurrence of an immune reaction against the organism's own cells or tissues. "However, it is unknown whether this amino acid substitution affects LAP2 interaction with lamin B1, has other functional consequences in other specific cell types, or is involved in susceptibility to autoimmunity." (PMID 34335680, 2021). "Moreover, the autophagy–lamin B1 axis is highly active in the aberrant ectopic GCs in the salivary glands of Sjögren’s disease, defining its role in autoimmunity." (PMID 40397664, 2025). "Although experimental evidence on the role of TMPO and LAP2 in autoimmunity is limited, it has been demonstrated that LAP2 binds to lamin B1 in vitro." (PMID 34335680, 2021).
autonomic dysfunction (2 papers, 2019 to 2025). "By contrast, the Italy-1 family was distinguished from others and defined as ADLD-1-TO because of variant features of the absence of the autonomic dysfunction, relative sparing of cerebellar WM, and the increased laminB1 mRNA without LMNB1 duplication." (PMID 31695592, 2019). "The possibility of LMNB1 gene-related ADLD should be considered when a patient presents with slow progressive limb weakness, especially spastic weakness and autonomic dysfunction, combined with MRI suggesting symmetric leukodystrophy and family members have similar clinical symptoms." (PMID 40046440, 2025).
bladder cancer (2 papers, 2023 to 2025). "Although not previously explored within HNSCC, LMNB1 is included within a panel of eight DNA damage repair genes associated with OS in bladder cancer." (PMID 40014866, 2025). "Previous studies showed that silencing ZKSCAN3 by small hairpin RNAs (shRNAs) in bladder cancer cells (UC13) can promote senescence of them, which may be due to the degradation of lamin B1 via autophagy, a type of selective autophagy—nuclear autophagy." (PMID 37175493, 2023).
breast invasive carcinoma (2 papers, 2022 to 2025). "Lower lamin A/C and lamin B1 expression; decreased levels of emerin in invasive breast cancer; downregulation of SUN1, SUN2, and nesprin‐2; upregulation of LBR." (PMID 39866838, 2025).
clear cell renal carcinoma (2 papers, 2022 to 2024). A malignant epithelial neoplasm of the kidney characterized by the presence of lipid-containing clear cells within a vascular network. "In contrast, a recent study revealed that lamin B1 overexpression is significantly associated with poor clinical outcomes in clear-cell renal cell carcinoma." (PMID 35328162, 2022). "Importantly, a large-scale tissue microarray analysis of 622 clear cell renal carcinoma (and their corresponding normal kidney tissue) revealed that lamin B1 is expressed in 80.87% of the tumor samples at a cut-off rate of ≥60% positive expression." (PMID 35328162, 2022).
diffuse large B-cell lymphoma (2 papers, 2022 to 2026). "Moreover, low LMNB1 expression is associated with poor clinical outcomes in patients with diffuse large B-cell lymphoma (DLBCL)." (PMID 42261377, 2026).
Emery-Dreifuss muscular dystrophy (2 papers, 2020 to 2021). Emery-Dreifuss muscular dystrophy (EDMD) is characterized by muscular weakness and atrophy, with early joint contractures and cardiomyopathy. "Interestingly, the authors found that expression of lamin A rod-domain mutants associated with the Emery-Dreifuss muscular dystrophy (EDMD), G232E, Q294P and R386K, considerably increased the expression of RNF123, which was associated with decreased protein levels of lamin B1, LAP2α and pRb." (PMID 32471220, 2020).
Hutchinson-Gilford progeria (2 papers, 2017 to 2022). "Interestingly, the multi-lobulated nuclei and lamin B1 staining are reminiscent of cells from Hutchinson-Gilford progeria patients carrying the lamin A 433G>A mutation (E145K)." (PMID 35464859, 2022). "In these cells, the nuclear envelope labelled by immunostaining of lamin B1 appears multi lobular and distorted, reminiscent of nuclei found in the premature ageing disease Hutchinson-Gilford progeria syndrome and in E145K cells." (PMID 35464859, 2022).
infertile (2 papers, 2024 to 2025). "Human endometriotic lesions (consisting of ectopic endometrium), often associated with infertility, exhibit increased expression of senescence markers like p16Ink4a and decreased lamin B1 (LMNB1)." (PMID 40643476, 2025). "Semen samples from 12 infertile patients (9 with complete globozoospermia and 3 with partial globozoospermia) and 10 normozoospermic men (control) were examined by transmission electron microscopy and immunocytochemistry with antibodies against lamin B1." (PMID 39045326, 2024).
lymph node metastasis (2 papers, 2015 to 2024). "Reduced amounts of lamin A/C and B2 increase risk for lymph node metastasis and disease specific death possibly through increased nuclear deformability while high expression of lamin B1 predicts disease recurrence." (PMID 26469707, 2015). "Our results show that decreased expression of A-type lamins is associated with elevated risk for lymph node metastasis and disease specific death while increased expression of lamin B1 is associated with BCR and local spread." (PMID 26469707, 2015).
mesothelioma (2 papers, 2021 to 2022). A usually malignant and aggressive neoplasm of the mesothelium which is often associated with exposure to asbestos. "However, published reports are at variance, for example knockdown of LMNB1 in mouse embryonic fibroblasts reduced miRNA-145 levels, whilst overexpression of miRNA-145 led to a reduction in LMNB1 in mesothelioma cells but not in rat cardiac myocytes." (PMID 33923614, 2021).
osteosarcoma (2 papers, 2020 to 2023). A usually aggressive malignant bone-forming mesenchymal neoplasm, predominantly affecting adolescents and young adults. "As regarding lamin B1, all osteosarcoma cell lines showed higher levels than normal osteoblasts." (PMID 32069980, 2020). "The expression and distribution of lamin A/C, lamin B1 and emerin were investigated by confocal laser scanning microscopy, western blot analysis and RT-PCR, and osteoblasts were considered as reference cells for the osteosarcoma cell lines." (PMID 32069980, 2020). "In contrast, a sample obtained from short-term survival osteosarcoma patient expressed high levels of lamin B1 and no detectable A/C-type lamin and emerin." (PMID 32069980, 2020).
pancreatic ductal adenocarcinoma (2 papers, 2022 to 2023). An infiltrating adenocarcinoma that arises from the epithelial cells of the pancreas.
rheumatoid arthritis (2 papers, 2022 to 2024). A chronic, systemic autoimmune disorder characterized by inflammation in the synovial membranes and articular surfaces. "Previously, LMNB1 mRNA was increased following IL-10 stimulation of rheumatoid arthritis synovial macrophages, suggesting a possible anti-inflammatory role, a feature that has been supported in other models." (PMID 36050729, 2022).
systemic lupus erythematosus (2 papers, 2006 to 2024). An autoimmune multi-organ disease typically associated with vasculopathy and autoantibody production. "In systemic lupus erythematosus a strong association of autoantibodies to human nuclear lamin B1 with lupus anticoagulant antibodies (LAC) has been reported and suggested that the presence of LAC without anti-lamin B1 may define a subset of SLE patients at greater risk for thrombosis." (PMID 16956395, 2006).
tauopathies (2 papers, 2019 to 2024). "Indeed, loss of lamin B1 is considered a biomarker of senescence and has been reported to underlie the progression of several tauopathies and neurodegenerative diseases." (PMID 31727161, 2019). "Moreover, LMNB1 dysfunction and its associated DNA heterochromatin relaxation have been identified in the D. melanogaster tauopathy model system and autopsy human AD brains, suggesting that tauopathies can be categorized into neurodegenerative laminopathies." (PMID 39596399, 2024).
virus infection (2 papers, 2020 to 2024). "These observed alterations were not due to regulation of host gene expression during virus infection as we did not detect any significant changes in lamin A/C and lamin B1 mRNA levels (data not shown)." (PMID 39288210, 2024). "Immunoblotting of cell lysates with anti-lamin A/C and lamin B1 revealed similar levels of full-length lamin A/C and lamin B1 in mock-infected and virus-infected cells, indicating that there was no change in the total lamin protein levels following virus infection." (PMID 32028682, 2020).
Werner syndrome (2 papers, 2013 to 2021). "It is possible that MAP kinase activation, which was previously observed in Werner syndrome, could also contribute to lamin B1-linked cellular senescence." (PMID 23849162, 2013).
age (1 paper, 2021). A temporal measurement of the time period elapsed since an identifiable point in the life cycle of an organism. "Lamins and its associated protein, especially Lamin A and Lamin B1, forms an interface with the nuclear membrane and nuclear pore complexes, while alteration of lamins involves in cellular premature senescence and age‐associated diseases." (PMID 33522656, 2021).